LGALS3 (galectin 3)
Diseases named in the same sentence as LGALS3 in open-access papers (continued):
Sharing a sentence is not in itself a finding about the gene and the disease.
heart failure (continued). "Both experimental and clinical studies have shown that galectin-3 is an independent predictor of all-cause mortality, cardiovascular death, and occurrence of heart failure following acute coronary syndrome." (PMID 31080833, 2019). "The same heart failure guideline writing group also identified several emerging blood biomarkers of interest associated with myocardial tissue activity such as soluble ST2 and galectin-3 for possible roles in heart failure risk stratification and management." (PMID 31882822, 2019). "Currently, the associations of Galectin-3 (Gal-3) with heart failure and ventricular remodeling attract increasing attention." (PMID 30967790, 2019). "Lgals3 and Ccl2 have both been implicated in a variety of processes associated with heart failure, including myofibroblast proliferation, fibrogenesis, tissue repair, inflammation, and ventricular remodeling, and both were therefore investigated in our model." (PMID 31354700, 2019). "For example, galectin-3 is associated with inflammation and fibrosis, is a known mediator of heart failure development and progression and is elevated significantly in NYHA I-IIIa vs. controls and further elevated in severe HF NYHA IIIB-IV." (PMID 30498496, 2018). "Based on studies in heart failure patients, galectin-3 was recently recommended as an additive for risk stratification in heart failure patients." (PMID 29327139, 2018). "Increased galectin-3 plasma concentration has been linked to an unfavorable outcome in patients with heart failure or atrial fibrillation (AF)." (PMID 29118378, 2017). "Measurements of galectin-3 plasma levels have recently entered AHA recommendation for stratification of heart failure risk." (PMID 29118378, 2017). "Our results support the possible usefulness of the combination of NT-proBNP, ST2, and Galectin-3 in order to identify the patients with the highest risk of heart failure progression in the short and mid-term follow-up." (PMID 29367540, 2017). "Galectin-3 concentrations in the circulation are associated with incident heart failure, atrial fibrillation, atherosclerosis and mortality." (PMID 28425846, 2017). "Here, we report that serum galectin-3 levels above the mean of 10 ng/mL andincreased PASP are independent prognostic factors for all-cause mortality andreadmissions of heart failure patients over a period of 12 months." (PMID 26760784, 2016). "Galectin 3 (Gal-3) reflects cardiac fibrosis in heart failure HF, but has also been associated to renal fibrosis and impaired renal function." (PMID 27246703, 2016). "Galectin-3 has been linked to interstitial cardiac fibrosis and is a purported prognostic marker in patients with heart failure." (PMID 28066244, 2016). "Galectin-3 is an important mediator that plays a pathogenic role in cardiac hypertrophy and heart failure." (PMID 28066244, 2016). "In a clinical study of patients with heart failure, increased circulating levels of galectin-3, used as a marker of cardiac fibrosis, were associated with an increased risk for incident heart failure." (PMID 28066244, 2016). "Galectin-3 independently predicted all-cause mortality and heart failure rehospitalisation, and yielded significant reclassification indices." (PMID 26942916, 2016). "The major finding of this study is that doxazosin caused a dose dependent increase in galectin-3 protein expression in HL-1 cardiomyocytes, a possible new mechanism of doxazosin induced higher incidence of heart failure in the ALLHAT study." (PMID 28066244, 2016). "In previous studies, increased galectin-3 levels were associated with adverse clinical outcomes in the general population and in patients with heart failure." (PMID 27089335, 2016). "ST2 and galectin-3 (Gal-3) are compared head-to-head for long-term risk stratification in an ambulatory heart failure (HF) population." (PMID 25949827, 2015).
heart failure (continued). "Human studies show that subjects with elevated galectin-3 levels have increased risk for developing heart failure, and blood testing for galectin-3 is now being used to monitor heart failure." (PMID 26047815, 2015). "The assumption that galectin-3 was one of the causes involved in the onset of heart failure was corroborated by infusing Gal-3 into the pericardial sac of wild type rats, which prompted extensive myocardial fibrosis." (PMID 25960597, 2015). "The presence and level of circulating galectin-3 (Gal-3), a member of the galectin family, is associated with diverse diseases ranging from heart failure, immune disorders to cancer metastasis and serves as a biomarker of diagnosis and treatment response." (PMID 24809457, 2014). "Its fibrotic action involves the activation not only of growth factors such as connective tissue growth factor (CTGF) but also new mediators such as galectin 3, which is associated with adverse long-term cardiovascular outcomes in patient with heart failure." (PMID 22844495, 2012). "While serum galectin-3 levels are an important risk factor in patients with heart failure, their prognostic implications are unknown in patients with CAD." (PMID 40747494, 2025). "While the associations between NT-proBNP, galectin-3, and cardiac remodeling, particularly under pathological conditions such as heart failure and hypertensive disorders, are well documented, further studies are necessary to elucidate the mechanisms underlying these newly discovered correlations." (PMID 40075783, 2025). "Furthermore, elevated levels of galectin-3 are associated with the severity of heart failure and poor clinical outcomes." (PMID 40918185, 2025). "Notably, Lgals3, previously implicated in heart failure and the post-MI remodeling response, became highly significant only after correction (Padj = 0.16 to 1e-7), highlighting it as a potential candidate for future investigation." (PMID 40705823, 2025). "Some other previous studies on galectin-3 have shown that galectin-3 can be used as a diagnostic or prognostic biomarker for heart failure, renal failure, and some types of cancer (thyroid carcinoma, hepatocellular carcinoma (HCC), endometrial tumor, osteosarcoma, etc.)." (PMID 38674175, 2024). "Also, patients withsevere obesity and elevated galectin-3 had >4-foldhigher risk of developing heart failure." (PMID 39139163, 2024). "The aim of this study was to investigate the potential role of sex-related differences in the following: risk factors, left ventricular (LV) structural and functional changes, coronary angiography, expression of the gal-3 encoding gene LGALS-3 and plasma gal-3 levels in heart failure (HF)." (PMID 39767568, 2024). "In brief, numerous risk factors, including coronary heart disease history, NT-proBNP levels, EF, waist circumference, BMI, and time to diagnosis of heart failure, were associated with increased galectin-3 levels in patients with heart failure with a reduced ejection fraction." (PMID 36673621, 2023). "Galectin-3, classified in the galectin family, is a protein that has been shown to be causally linked to pathophysiological cardiovascular processes, including atherosclerosis, fibrosis, and heart failure." (PMID 36959138, 2023). "The results, despite being based on small cohort studies, inform that galectin-3 could serve as a potential biomarker in cardiovascular risk stratification in children with heart failure, arrhythmia, Kawasaki disease or in patients undergoing cardiac surgery." (PMID 35410028, 2022). "Thus, the Guidelines for the Management of Heart Failure by the American Heart Association indicate galectin-3 as an additional biomarker for the prognosis and risk stratification in patients with heart failure (COR IIb)." (PMID 35410028, 2022). "In addition to LGE-MRI, galectin-3 seems to play an important role in the sudden death risk stratification of heart failure patients." (PMID 35628969, 2022).
heart failure (continued). "In 2017, the American Heart Association recommended that plasma levels of galectin-3 could be used as a risk factor and prognosis biomarker of heart failure." (PMID 36272642, 2022). "In addition, galectin-3 expression is known tobe associated with heart failure, inflammation, fibrogenesis and ventricularremodelling." (PMID 39077714, 2022). "This speculation has been verified by a number of clinical studies showing that higher circulating concentrations of galectin-3 are associated with an increased risk of heart failure, coronary artery disease, ischemic stroke, and cardiovascular mortality." (PMID 36175599, 2022). "Circulating galectin-3 has been suggested as a potential biomarker for diabetic nephropathy progression and cardiovascular disease prognosis linked to myocardial fibrosis, tissue remodelling, and heart failure development." (PMID 35008648, 2021). "Galectin-3 was elevated in breast, colon, and lung cancer in our data; however, galectin-3 is also implicated in a variety of diseases, including heart failure with reduced ejection fraction, chronic obstructive pulmonary disease, diabetes mellitus, and chronic kidney disease." (PMID 34638303, 2021). "Galectin-3 has diagnostic value for heart failure with preserved ejection fraction." (PMID 35141299, 2021). "We discussed the potential utility of galectin-3 as a diagnostic and disease severity/prognostic biomarker in different cardio/cerebrovascular diseases, such as acute ischemic stroke, acute coronary syndromes, heart failure and arrhythmogenic cardiomyopathy." (PMID 35053194, 2021). "In patients with cardiovascular risk factors, serum concentrations of galectin-3 showed an inverse association with anxiety, which was independent of both the severity of physical impairment and established risk factors for the progression of heart failure." (PMID 33024450, 2020). "In addition Tetranectin gene was associated with gene expression of the cardiac fibrosis and heart failure biomarker galectin-3 (r = 0.59, p = 0.0004)." (PMID 32371911, 2020). "Importantly, Galectin 3 has emerged as an independent predictor of all-cause mortality, cardiovascular death, and the occurrence of heart failure following acute coronary syndromes." (PMID 31035456, 2019). "Galectin-3 has been evaluated as an important biomarker of heart failure and cardiac fibrosis and may also be associated with renal fibrosis." (PMID 31080833, 2019). "In particular, recommendations for the measurement of galectin-3 are included in the American College of Cardiology Foundation and the American Heart Association guidelines to aid in risk stratification in patients with heart failure." (PMID 29414883, 2018). "Studies have evaluated the association of galectin-3 and outcome in patients with heart failure." (PMID 30018673, 2018). "Galectin-3 (Gal-3), a β-galactoside-binding lectin, has been implicated in myocardial fibrosis, development of left ventricular (LV) dysfunction and transition from compensated LV hypertrophy to overt heart failure (HF), being a novel prognostic marker in HF." (PMID 28468272, 2017). "Interestingly, several works have shown that the upregulation of LGALS3 is linked to heart failure and is an independent blood biomarker for ventricular remodeling and mortality." (PMID 25329529, 2014). "Experimental observations suggest that galectin-3 may be regarded not only as a biomarker but also as an active mediator of fibrosis causing progression of heart failure." (PMID 24156746, 2013). "MetS was previously linked to high plasma galectin-3 levels, and the combination of MetS with galectin-3 above the 75th percentile significantly increases heart failure risks more than four-fold (over a four-fold higher long-term risk to develop heart failure)." (PMID 41590667, 2026).
heart failure (continued). "NT-proBNP, cTn, sST2, and galectin-3 are cardiac biomarkers that may be useful in real-time to help presage the structural and functional changes associated with clinical recovery in heart failure patients and thus may help guide clinical management (Central Illustration)." (PMID 37089891, 2023). "In addition, galectin-3 has been implicated in metabolism and in insulin resistance; in patients with heart failure, especially heart failure with a reduced ejection fraction, there was a higher rate of insulin resistance than in the group with a preserved ejection fraction." (PMID 36673621, 2023). "Also, serum galectin-3 and NT-proBNP levels were much higher in the high Qa group, indicating a close relationship between the high Qa, increased myocardial fibrosis, and the risk of heart failure (HF) in HD patients." (PMID 35966517, 2022). "Galectin-3 is a known marker of cardiac fibrosis; higher levels of this protein have been previously shown to be associated with an increased risk of heart failure and all-cause mortality in community populations, as well as with risk of morbidity and mortality amongst patients with heart failure." (PMID 34362097, 2021). "Besides the predictive role of Galectin-3 in heart failure in terms of morbidity and mortality, it may be causally involved in mechanisms of tubulointerstitial renal fibrosis and CKD progression." (PMID 33344515, 2020). "In fact, the correlations of these factors, such as left atrial size, duration of AF, left ventricular ejection fraction, presence of heart failure, BMI, and medication used (including stains) with galectin-3 may confound the potential association between galectin-3 and AF recurrence." (PMID 31772609, 2019). "However, we also conducted experiments in the murine model of DCM and observed galectin-3 positive cells infiltration, suggesting that our findings may be generalizable to other forms of heart failure associated with galectin-3." (PMID 30673749, 2019). "Galectin-3 (Gal-3), a β-galactoside-binding lectin, has been implicated in myocardial fibrosis, development of left ventricular (LV) dysfunction and transition from compensated left ventricular (LV) hypertrophy to overt heart failure (HF) in various experimental HF models." (PMID 28468272, 2017). "It will be interesting to know whether p38 MAP kinase and/or FAK signaling pathways are involved in doxazosin stimulated galectin-3 expression and whether the increased heart failure risk by doxazosin is due to activating specific receptors like hERG in heart muscle cells." (PMID 28066244, 2016). "Macrophage-derived Galectin-3 (Gal-3), an emerging biomarker, reflects myocardial fibrosis, particularly relevant in heart failure." (PMID 40725061, 2025). "In patients with heart failure with reduced ejection fraction (HFrEF), miR-210-3p, along with NT-proBNP, sST2, and galectin-3, was significantly elevated compared to those with HFpEF." (PMID 41226851, 2025). "When combined with BNP, galectin-3 improves predictive accuracy in patients discharged after an acute decompensated heart failure episode, offering better prognostic value than BNP alone." (PMID 39941305, 2025). "The primary keywords in this cluster include galectin-3, heart failure, cardiac fibrosis, inflammation, and myocardial infarction." (PMID 40747108, 2025). "Galectin-3 is a well-established biomarker on the predictor of cardiovascular events in patients with heart failure." (PMID 40747494, 2025). "Numerous studies describe the implication of galectin-3 in the pathogenesis of many important human diseases, including heart failure, chronic kidney disease, liver and pulmonary fibrosis, as well as cancer." (PMID 41373557, 2025). "In general, galectin-3 has shown promise in predicting heart failure beyond traditional biomarkers like NPs and cardiac troponins." (PMID 39129285, 2025).
heart failure (continued). "In the context of cardiovascular disease, galectin-3 is produced in response to myocardial injury and stress, often serving as a marker of adverse cardiac remodeling and heart failure." (PMID 40430046, 2025). "The most frequently occurring keyword is “Heart Failure,” appearing 476 times, followed by “Galectin-3” with 380 occurrences and “Biomarker” with 320 occurrences." (PMID 40747108, 2025). "This study aimed to compare the expression levels of microRNA-210-3p with biomarkers NT-proBNP, sST2, and galectin-3, in heart failure patients with preserved and reduced ejection fractions." (PMID 40179320, 2025). "Growing evidence supports the utility of biomarkers such as Galectin-3 (Gal-3), soluble ST2 (sST2), and soluble urokinase plasminogen activator receptor (suPAR) for risk stratification in heart failure, including HIV-associated cardiomyopathy." (PMID 41019440, 2025). "In many studies, galectin-3 is described as a novel prognostic biomarker with a strong predictive value for cardiovascular mortality and hospital re-admission in heart failure (HF), conditions that are prevalent in patients with OSA." (PMID 39941305, 2025). "In addition to suPAR, galectin-3, a key regulator of fibrosis and inflammation, is strongly associated with cardiac remodeling, hepatic fibrosis, and kidney disease progression, with elevated levels linked to higher mortality in heart failure (HF) and liver fibrosis." (PMID 41235339, 2025). "Based on this platform, the immunosensor exhibited a linear response with great sensitivity, stability, reproducibility, and selectivity toward the heart failure biomarker Galectin‐3 (Gal‐3)." (PMID 40270437, 2025). "The prognostic accuracy of sST2 is comparable in both heart failure with reduced ejection fraction (HFrEF) and preserved ejection fraction (HFpEF), and it outperforms Galectin-3 (Gal-3) in patients with chronic heart failure." (PMID 40869365, 2025). "Galectin-3 (gal-3), a galactoside-binding lectin, is a promising new cardiac biomarker, which was included in the 2013 heart failure management guide and confirmed to have the function of detecting the risk of adverse events." (PMID 38680895, 2024). "Despite the lack of literature data on the relationship between these factors, it should be noted that both galectin-3 and creatinine kinase are mentioned by researchers as markers of heart failure and myocardial infarction." (PMID 39451549, 2024). "Comparative analyses of emerging biomarkers, such as galectin-3 and sST2, have shown that sST2 offers superior prognostic value in patients with heart failure." (PMID 39685669, 2024). "This underscores the potential of targeting galectin-3 as a therapeutic strategy to prevent heart failure." (PMID 39063659, 2024). "Galectin-3 (Gal-3) is crucial in heart failure (HF) by contributing significantly to cardiac ventricular remodeling." (PMID 39432214, 2024). "In the ARIC study, galectin-3 levels were significantly higher in patients with AF, but the significance decreased in patients with AF along with heart failure and coronary artery disease." (PMID 38892886, 2024). "Clinical trials are actively investigating the safety and efficacy of galectin-3 inhibitors in heart failure patients, particularly those with preserved ejection fraction." (PMID 39063659, 2024). "Meanwhile, BNP (B-type natriuretic peptide), another well-established biomarker in heart failure, complements galectin-3 in assessing and managing diastolic dysfunction." (PMID 39063659, 2024). "A number of studies have examined the relationship between galectin-3 levels and cardiac fibrosis in heart failure." (PMID 39451549, 2024). "Galectin-3 plays a role in several diseases and has been described as a biomarker for different types of cancer, liver disease, kidney disease, and heart failure." (PMID 38731984, 2024).